IGFBP1 (insulin like growth factor binding protein 1)
Diseases named in the same sentence as IGFBP1 in open-access papers (continued):
Sharing a sentence is not in itself a finding about the gene and the disease.
Hyperinsulinemia (continued). "Low levels of serum Insulin-like Growth Factor-Binding Protein-1 (IGFBP-1) in PCOS women led to the hypothesis that hyperinsulinemia in PCOS inhibits the production of IGFBP-1, which in turn stimulates excessive androgen production." (PMID 30775682, 2018). "Therefore, the reduction of IGFBP-1 in T1D is thought to be caused by the insulin deficiency in the patients, although in T2D patients with short duration, the decreased IGFBP-1 concentrations are mainly due to hyperinsulinemia." (PMID 24904693, 2014). "Hyperinsulinemia leads to increase of bioavailable IGF by inhibiting IGFBP1 in liver and may also sensitize cells to this hormone." (PMID 23476808, 2013). "IGFBP-1 and IGFBP-2 levels are inversely associated with insulin levels, which suggests that chronic hyperinsulinemia could depress binding protein interaction and thus increase free IGF-I." (PMID 20148110, 2010). "An alternative explanation is that low levels of IGFBP1 in GDM are a consequence of hyperinsulinemia with another upstream cause, but this would not be consistent with the rise of circulating IGFBP1 throughout pregnancy (which is characterized by progressive hyperinsulinemia)." (PMID 38627562, 2024). "Furthermore, low IGFBP-1, indicating hyperinsulinemia, improved in the T2D group." (PMID 39273678, 2024). "Low circulating IGFBP-1 levels may be a marker of hyperinsulinemia." (PMID 36901984, 2023). "However, in patients with hyperinsulinemia not only is more insulin secreted, but the production of IGFBP-1 and IGFBP-2 is diminished, therefore permitting a higher concentration of active IGF-1 which can stimulate insulin receptors (IR) on endometrial tumor cells." (PMID 35439978, 2022). "Hyperinsulinemia causes hyperandrogenism through elevation of sex hormone free fractions due to decreased SHBG (sexual hormone binding globulin), increased hepatic insulin-like growth factor-1 (IGF-1) production, and/or increased IGF-1 bioavailability through a reduction in IGFBP-1 generation." (PMID 34574647, 2021). "In addition, hyperinsulinemia also increases IGF-I bioavailability through the downregulation of insulin-like growth factor binding protein-1 (IGFBP-1) and IGFBP-2, which both may inhibit IGF-I actions." (PMID 34360563, 2021). "It is known that hyperinsulinemia, a characteristic that was observed in our sample, induces a higher production of IGF-1 and lower production of IGFBP-1 (Insulin-like growth factor-binding protein 1) by the liver." (PMID 35703718, 2022). "Among these factors are the severity of hyperinsulinemia and HA, the blood levels of the binding proteins for insulin, IGF-1 (IGFBP-1) and androgens (SHBG), and the blood levels of AMH and HDL-C." (PMID 33429918, 2021). "For instance, a decrease in IGFBP1 production leads to a reduction in IGF-1 levels, and it is capable of inducing hyperinsulinemia and abnormal glucose clearance." (PMID 31601230, 2019). "In addition, hyperinsulinemia leads to decreased hepatic synthesis of insulin-like growth factor (IGF)-binding protein 1 (IGFBP-1) and protein 2 (IGFBP-2) and may result in increased bioactivity of IGF-I, which directly induces the development of CRC due to its mitogenic and antiapoptotic actions." (PMID 31681585, 2019). "On the other hand, IGFBP-1 and IGFBP-2 have a well-known role in metabolic regulation, maintaining blood glucose levels, insulin sensitivity, glucose intolerance, and hyperinsulinemia." (PMID 26858687, 2016). "Additionally, hyperinsulinemia in PCOS is known to increase the bioavailability of IGF1 via the downregulation of its carrier protein, i.e., IGFBP1." (PMID 30975191, 2019). "We suggest that there is also an IR to IGFBP-1 regulation in SGA infants and that hyperinsulinism secondary to IR may have led to these changes in the IGF-IGFBP axis in SGA infants." (PMID 23748063, 2013).
Hyperinsulinemia (continued). "Insulin impairs IGFBP-1 gene expression, and, as a consequence, high levels of IGFBP-1 are present in diabetes mellitus and low levels are noted during hypoglycaemia in patients with congenital hyperinsulinism." (PMID 24228030, 2013). "Hyperinsulinemia synergizes with LH on theca cells, upregulating CYP17A1 transcription and cytochrome P450 17α-hydroxylase (P450c17α) activity while simultaneously lowering hepatic sex hormone-binding globulin (SHBG) and insulin-like growth factor-binding protein-1 (IGFBP-1)." (PMID 41294822, 2025). "By peripherally inhibiting hepatic synthesis, hyperinsulinemia decreases serum sex hormone binding globulin (SHBG), favoring free circulating androgens, and decreasing insulin-like growth factor binding protein-1 (IGFBP-1), allowing more IGF-1 to be accessible locally and peripherally." (PMID 37791160, 2023). "Furthermore, hyperinsulinism observed in PCOS patients lowers the concentration of circulating glycodelin (biomarker of endometrial function) and insulin-like growth factor-binding protein-1 (IGFBP-1), a feto-maternal interface adhesion factor." (PMID 34552924, 2021). "However, IGFBP-1 levels rise during the development of T2D, regardless of persisting hyperinsulinemia, indicating increased hepatic IR during CVD progression." (PMID 33905470, 2020). "In patients without hyperinsulinemia, IGF binding proteins (IGFBP-1 and IGFBP-2) control the amount of active IGF-1 that can act on cells to induce cell proliferation." (PMID 35439978, 2022).
Obesity (68 papers, 2007 to 2025). Accumulation of substantial excess body fat. "IGFBP-1 has a long-established inverse association with obesity, which is likely mediated by changes to insulin levels." (PMID 40987470, 2025). "The fibrilin 1 (FBN1) gene, which encodes the asprosin hormone, interacts only with IGFBP1 in the stress-induced obesity network." (PMID 39062927, 2024). "In this study we investigated the association between obesity and the levels of various IGFBPs (particularly, IGFBP-1, 3 and 7) in a group of Kuwaiti adolescents." (PMID 34394011, 2021). "In mice, an association has also been demonstrated between decreased IGFBP1 mRNA expression and obesity." (PMID 34371941, 2021). "Of these, IGFBP-1 has been consistently shown to be inversely associated with overweight and obesity, plasma insulin and glucose levels, as well as fasting plasma leptin levels." (PMID 34394011, 2021). "Several studies have shown that IGFBP-1 levels are correlated with BMI, raising the possibility that IGFBP-1 is implicated in obesity." (PMID 32190801, 2020). "In line with these experimental findings, several cross-sectional and prospective epidemiologic studies have associated low IGFBP-1 levels with obesity, high fasting insulin, impaired glucose tolerance, and diabetes in middle-aged individuals." (PMID 32492897, 2020). "Increased IGFBP-2 concentrations are protective against the development of obesity and improve insulin sensitivity, while higher IGFBP-1 concentrations are associated with lower insulin levels." (PMID 23516412, 2013). "The limitation could result from the inability to project a similar association between IGFBP-1 and obesity into other age groups." (PMID 34394011, 2021). "Therefore, a prospective study will possibly help delineate if the increased level of Hs-CRP are the cause or the consequence of lower level of IGFBP-1 in children with obesity." (PMID 34394011, 2021). "Therefore, the fact that IGFBP-1 was more strongly associated with WC/Ht ratio than the BMI z-scores makes IGFBP-1 a sensitive biomarker for obesity-related metabolic abnormalities." (PMID 34394011, 2021). "In addition, children with overweight or obesity tend to have lower concentrations of IL-10 and IGFBP-1, which can predispose them to low grade inflammation often reflected in higher circulating levels of CRP and resistin." (PMID 33266497, 2020). "The metabolic alterations associated with obesity, including changes in insulin and insulin-like growth factor binding protein 1 (IGFBP-1) serum levels (which result in increased circulating free IGF-1 levels), are also significantly correlated with breast cancer recurrence and mortality." (PMID 23880059, 2013). "In addition, the administration of caffeine in mice resulted in decreased or increased levels of certain proteins, such as Insig2, Rbp4, and Igfbp1, which have been associated with improved obesity, type 2 diabetes mellitus (T2DM), and cardiovascular pathologies." (PMID 38188177, 2024). "IGFBP1 promotes neovascularization in response to ischemia, is required for the endothelium to respond appropriately to injury and may be implicated in obesity." (PMID 35069436, 2021). "Moreover, glucose metabolism-associated genes, glucose-6-phosphatase (G6pc) and insulin-like growth factor binding protein 1 (Igfbp1), were down-regulated, accompanied with adrenoceptor β 3 (Adrb3) whose gene polymorphism is related to type 2 diabetes and obesity up-regulated." (PMID 34735568, 2021). "We found evidence suggesting a mediating role of SHBG, fasting insulin, bioavailable testosterone, and IGFBP-1 in the effects of ASAT on obesity-related cancers." (PMID 40987470, 2025). "A 5:2 diet with a 75% calorie restriction over six months in premenopausal women with obesity dramatically elevated IGFBP-1 and decreased IGF-1." (PMID 41439931, 2025). "In line with this, in vivo injection of an active IGFBP1 peptide improved insulin sensitivity in a diet-induced obesity mouse model." (PMID 38627562, 2024).
Obesity (continued). "Three proteins underexpressed with obesity (IGFBP1, BPIFB1 and COL4A1) were clustered in the turquoise cluster and overlapped with ER lumen and collagen-containing extracellular matrix GO terms." (PMID 38548792, 2024). "Previous studies suggest that IGFBP2 plays a role in diabetes and obesity mainly via regulation of IGFBP1." (PMID 36712921, 2023). "Because GKO mice are protected from HCD-induced obesity, we wanted to assess hepatic Igfbp1 expression in HCD feeding for 10 days." (PMID 36498997, 2022). "Together these data further illustrate the possibility of using IGFBP-1 as a sensitive marker for obesity-related inflammation and its related comorbidities." (PMID 34394011, 2021). "In the setting of obesity, we found that IGFBP-1 enhanced whole-body glucose tolerance and insulin sensitivity through interaction of its RGD domain with cell surface integrin receptors." (PMID 32190801, 2020). "Another study has reported that IGFBP-1 concentrations are repressed in response to increased insulin levels in obesity, and that low IGFBP-1 concentrations forecast the development of T2D." (PMID 33905470, 2020). "Other genes involved in obesity (e.g., Cidec, Cd36), diabetes (Igfbp1), inflammation (Cd63), mitochondrial function (Pdk4) and cancer (H19) were also upregulated by the soybean oil diet." (PMID 26200659, 2015). "IGF-binding protein (IGFBP)-1 levels are suppressed in relation to the increase in insulin levels in obesity and low levels predict the development of type 2 diabetes several years later." (PMID 26237614, 2014). "Low Igfbp1 levels are considered to be markers of metabolic syndrome and the Igfbp1 transgenic mice are protected from diet-induced obesity, a trait shared by the CD38-null mice." (PMID 21937766, 2011). "However, IGFBP1 concentrations can be influenced by non-obesity-related factors such as growth stage, acute inflammation, or nutritional status, which should be addressed in future studies." (PMID 40943443, 2025). "IGFBP-1 has been proposed as another potential marker for IR in children with obesity." (PMID 40278381, 2025). "We conclude that serum IGFBP-1 is an important prognostic factor for long-term poststroke functional outcome, and might play a minor part in what is commonly referred to as the “obesity paradox”." (PMID 38732147, 2024). "A recent study identified six proteins (LEPR, IGFBP1, WFIKKN2, AGER, DPT, and CTSA), including WFIKKN2, which may have a causal role in the development of obesity." (PMID 39273278, 2024). "IGFBP1 was involved in glucose metabolism and molecular regulation of obesity." (PMID 38614964, 2024). "In addition, IGFBP1 was identified as potential target in the previous MR analyses of plasma proteome in obesity." (PMID 38614964, 2024). "In mice with diet-induced obesity, the overexpression of IGFBP-1 improved insulin sensitivity." (PMID 38928106, 2024). "Our data demonstrate a strong negative association of IGFBP-1 with overweight/obesity, and the inflammatory marker Hs-CRP." (PMID 34394011, 2021). "The study also reported lower level of IGFBP-1 with obesity." (PMID 34394011, 2021). "Since, a strong negative association was detected between the level of IGFBP-1 with overweight and obesity in adolescents." (PMID 34394011, 2021). "Metabolic phenotype was similar in IGFBP-1 knockout and wild-type mice subjected to obesity." (PMID 32190801, 2020). "Obesity is associated with disturbances in the IGF-I axis; an inverted U-shaped association between BMI and IGF-I has been observed, while BMI and concentrations of IGFBP-1 and -2 have been shown to be inversely associated." (PMID 28701188, 2017). "In conclusion, IGFBP-1 is identified as a novel target of ghrelin action in liver that may contribute to its metabolic effects in obesity." (PMID 24555152, 2013).
Obesity (continued). "However, the drug Mecasermin targeting IGFBP1 has been approved to treat growth failure in pediatric patients with primary IGF-1 deficiency or with growth hormone gene deletion and is likely to be used for treating obesity." (PMID 38614964, 2024). "If IGFBP1 is acting beneficially, then by reducing the levels of hepatic oleic acid, either by dietary or pharmacological intervention, may be an effective form of treating HCD-induced obesity and the associated metabolic dysfunction." (PMID 36498997, 2022). "Therefore we suggest that IGFBP-1 could potentially be used as a sensitive biomarker for obesity and its subsequent effects in screening and monitoring of obesity-related metabolic complications in adolescents." (PMID 34394011, 2021). "Although beyond the scope of this study, additional experiments involving whole genome methylation profiling, or assessment of methylation of genes such as PPARGC1A, IGFBP-1, and SLC6A4, which have previously been shown to be associated with T2D and obesity, may be beneficial." (PMID 34485290, 2021). "Thus IGFBP-1 is identified as a novel target of ghrelin action in liver that may contribute to the spectrum of metabolic actions of ghrelin in obesity." (PMID 24555152, 2013). "BMI-predictive proteins included established obesity markers and obesity-related proteins, including adiponectin, CRP, IGFBP1, IGFBP2, PRG4, SHBG, apolipoproteins (APOA4, APOF) and inflammatory response proteins (A2M, APCS, LBP, HSPG2, HP, AOC3, ITGB1, VNN1)." (PMID 39972214, 2025). "Three protein markers: IGFBP1, BPIFB1 and COL4A1 were significantly underexpressed, comparing between participants with obesity and NOH group." (PMID 38548792, 2024). "A comparison of the obesity and control groups revealed differences in the expression of IGF2, IGFBP1, and IGFBP7 genes." (PMID 34371941, 2021). "A secondary aim was to evaluate the relationships of IGFBP-1 and MMP-8 with the degree of obesity as well as the dietary intake of energy yielding nutrients, vitamins and minerals." (PMID 32923723, 2020). "IGFBP1 and IGFBP2 were consistently reduced in children with obesity, along with adiponectin." (PMID 39972214, 2025). "Obesity leads to enhanced circulating levels of insulin, IGF-I, IGF-II and IGF-binding proteins (IGFBP-3), while reducing levels of the low molecular weight IGF-binding proteins (IGFBP-1, IGFBP-2)." (PMID 38260836, 2023). "Especially interesting and promising target molecules for obesity-derived implications in placenta could be CCL2, PRL, MMP12, TAC3, PRG2 and IGFBP1 that were the most dysregulated genes among our study group." (PMID 28125591, 2017). "Indeed, the binding regions of EP300, CEBPB, and HDAC2 in the promoters of transferrin (TF), insulin-like growth factor binding protein 1 (IGFBP1) and NQO1, whose expression was increased in obesity and was normalized by CR or RSV, overlap." (PMID 26441656, 2015). "It appears likely that sensitivity to insulin in obesity is preserved in some tissues where it plays a central role in the GH-IGF axis response, by inhibiting pituitary GH, increasing hepatic GH responsiveness and suppressing hepatic IGFBP-1 secretion." (PMID 26237614, 2014). "It is speculated that ghrelin, which is decreased in simple obesity but increased in PWS, might play a role in blocking the inhibitory effect of insulin on IGFBP-1 production." (PMID 26237614, 2014). "Altered liver expression of IGFBP1 and G6P has been reported in patients with NASH and metallothioneins may play preventive roles against obesity through reduction of oxidative stress." (PMID 24324835, 2013). "IR did not correlate with the MMPs, ADAMS, ADAMTS, or IGF-1/IGFBP-1 when BMI was accounted for, suggesting that it is obesity which is accompanied by IR, rather than IR alone, that may modulate these ECM parameters in PCOS." (PMID 39796177, 2025).
Obesity (continued). "The transient changes in IGFBP1 and IGFBP3 at 2 weeks after surgery and their relationship to changes in FFA and hsCRP point to a previously unknown link between IGFBPs and adipose tissue function and low-grade inflammation in obesity." (PMID 36959287, 2023). "After high-fat feeding, IGFBP-1-KO mice had comparable body mass, glucose homeostasis, and insulin sensitivity, indicating that IGFBP-1 is not causally implicated in protection from obesity and obesity-impaired glucose tolerance." (PMID 32190801, 2020). "Interestingly, trending increases were detected for IGFBP-1 in non-obese tumor-free donors versus those with obesity (P = 0.05) and in non-obese ccRCC subjects versus non-obese tumor-free donors (P = 0.08)." (PMID 32469992, 2020). "IGFBP-1 was uniquely decreased in ccRCC subjects with obesity versus non-obese ccRCC subjects." (PMID 32469992, 2020). "Notably, we found that IGFBP-1 was the only factor to be decreased in the plasma of ccRCC subjects with obesity versus their non-obese ccRCC counterparts." (PMID 32469992, 2020). "In addition, altered mRNA expression of Pgc1a and Igfbp1 may be potentially related to the phenotypes of resistance to obesity but no obvious changes in dyslipidemia and glucose intolerance in Cnot4 Het mice." (PMID 40424271, 2025). "The concentration of IGFBP‐1 in participants without obesity was not statistically different from pre‐exercise levels at any time point after the start of the exercise session, and the same statistical findings were observed for participants with obesity (p > 0.05)." (PMID 40574473, 2025). "However, to our knowledge, no study has investigated whether s-IGFBP-1 could explain the obesity paradox in stroke." (PMID 38732147, 2024). "Another study of 150 participants (100 with obesity and 50 without obesity) in the Netherlands found that SELE, IGFBP1 and RARRES2 were significantly different between participants with obesity versus without obesity." (PMID 38548792, 2024). "Patients with Prader-Willi syndrome (PWS) have severe obesity and low GH, IGF-I and fIGF-I concentrations despite non-suppressed IGFBP-1 levels." (PMID 26237614, 2014). "In our case series, at baseline the activity of the GH-insulin-like growth factor-1 (IGF-1) system was impaired with low GH values, low total IGF-1 and in relation to the obesity low levels of free IGF-1 and non-suppressed IGF-binding-protein-1 (IGFBP-1)." (PMID 19128470, 2009). "In addition, the extent to which IGFBP-1 and MMP-8 may be modified by dietary intake has not been studied, although a link with human nutritional status, like obesity, has been reported." (PMID 32923723, 2020).